FGF21 (fibroblast growth factor 21)
Diseases named in the same sentence as FGF21 in open-access papers (continued):
Sharing a sentence is not in itself a finding about the gene and the disease.
metabolic syndrome (continued). "Of interest, positive associations of FGF21 with testosterone levels have been reported in women with polycystic ovarian syndrome (PCOS), and positive associations of irisin and FGF21 with testosterone levels may reflect associations of these hormones with components of the metabolic syndrome." (PMID 24926783, 2014). "Fibroblast Growth Factor 21 (FGF21) is a novel metabolic factor with effect on glucose and lipid metabolism, and shown to be elevated in diseases related to metabolic syndrome." (PMID 24883065, 2014). "Multivariate logistic regression analysis was structured with independent variables of age, sex, BMI, WC, HOMA-IR, FGF21, smoking status, hyperglycemia, family history of CAD, hypertension, NAFLD, and dyslipidemia." (PMID 23981342, 2013). "Human studies failed to prove the glucose-lowering potential of FGF21, but improvements in dyslipidemia and fatty liver disease have been presented." (PMID 39452947, 2024). "In a study comparing individuals with and without metabolic syndrome, higher FGF21 levels were observed in patients with metabolic syndrome." (PMID 39008201, 2024). "As such, FGF21 represents a potential therapeutic agent for the management of T2D and metabolic syndrome (although FGF21 analogues do not appear to lower blood glucose in human-based studies)." (PMID 37367914, 2023). "It is known that resistance activities such as push-ups or squats have effects on metabolic syndrome and lead to insulin sensitivity improvement and ALT reduction, and decreases in the cytokeratin 18 (CK18) and FGF21 levels were observed after applying this type of PA." (PMID 36902639, 2023). "Fgf21 stimulates glucose uptake in adipocytes, improves insulin sensitivity and glycemic control, enhances BAT thermogenesis and ameliorates dyslipidemia, so its overexpression in L-HFD animals may represent an attempt to overcome the metabolic derangements." (PMID 36768493, 2023). "In addition, we also listed several novel identified modulatory biomarkers which play an important role in the regulation of dyslipidemia induced by hypothyroidism, including PCSK9, ANGPTL3, ANGPTL8, FGF-21, FGF-19, and several microRNAs." (PMID 34784265, 2022). "This review will discuss FGF21-mediated FGFR1/β-KL signaling pathways in the liver, adipose, and cardiovascular systems, as well as how this signaling is involved in the interplay of these organs during the metabolic syndrome." (PMID 35983184, 2022). "FGF21 levels have been shown to be elevated 2–3 fold in oral glucose tolerance tests for patients with metabolic syndrome but not among healthy subjects." (PMID 36213282, 2022). "Overall, FGF-21 exerts beneficial vascular effects, possibly by mitigating vascular inflammation and dyslipidemia, independent of its antiobese and antidiabetic activity." (PMID 35186330, 2022). "In addition, ChREBP induces the expression of fibroblast growth factor 21 (FGF21), which ameliorates dyslipidemia in humans." (PMID 34203484, 2021). "FGF21 analogues tested in overweight/obese patients with T2D are able to reduce dyslipidemia and steatosis, but no improvement in glycemic and body weight was obtained." (PMID 31546675, 2019). "Fasting induces hepatic NR4A1, which may bind to the putative NBRE of the fibroblast growth factor-21 (FGF21) promoter and regulate FGF21 expression, which plays pivotal roles in the treatment of metabolic syndromes." (PMID 30013988, 2018). "FGF21 is proposed as a mediator of glucagon regulation of glucose and lipid metabolism and is an independent predictor of the metabolic syndrome in adults but not in children." (PMID 26379757, 2015). "FGF21 is a unique member of the FGF family and plays a significant role in regulating glucose and lipid metabolism, including stimulating glucose uptake insulin-independently, improving hyperglycemia and dyslipidemia." (PMID 24895642, 2014).
metabolic syndrome (continued). "Fibroblast growth factor 21 (FGF21) is a unique member of the FGF family and has broad metabolic functions, including stimulating glucose uptake insulin-independently and improving hyperglycemia and dyslipidemia." (PMID 24900988, 2014). "Another possible explanation could be that if atherosclerosis and metabolic syndrome, both aggravated by smoking, are the actual triggers for the FGF21 elevation in these subjects, their effects may not be fully reversible or may require more time to subside." (PMID 41384608, 2026). "However, FGF21 LKO failed to rescue OVX-induced dyslipidemia in females, as both TG and FFA levels were comparable (p > 0.05) between OVX+FGF21 LKO and OVX mice." (PMID 37834368, 2023). "The exploration of the correlation and predictive value of FGF21 level in T2DM, CAS and HP may provide evidence for further selection of FGF21 analogities instead of drugs in the treatment of metabolic syndrome and its related cardiovascular and cerebrovascular diseases." (PMID 38057786, 2023). "Consistently, treatment with FGF-21 has been confirmed to improve the energy metabolism in hepatocytes in both rodents and non-human primates, supporting that FGF21 could be considered as a potential therapeutic method for dyslipidemia." (PMID 34784265, 2022). "Moreover, the FGF-21 level was higher in COVID-19 patients diagnosed with metabolic syndrome than in patients without metabolic syndrome." (PMID 34680053, 2021). "For reasons that are still unknown, the glucose-lowering effects of pharmacological FGF21 are absent or less pronounced in humans, while its effects on dyslipidemia are highly conserved between rodents and humans." (PMID 35046901, 2021). "Furthermore, they have no abnormality in carbohydrate metabolism and overproduce Fgf21, a protective factor in the metabolic syndrome." (PMID 34473777, 2021). "PPGL with metabolic syndrome or dyslipidemia showed higher FGF21 than those without (p < 0.001)." (PMID 30959789, 2019). "Thus, the observed rise in FGF21 in LP-treated mice could reflect an adaptive hormonal response contributing to the amelioration of dyslipidemia rather than a simple compensatory elevation." (PMID 41470800, 2025). "Furthermore, FGF21 resistance has also been observed in clinical reports where the serum FGF21 level was significantly increased in patients with nonalcoholic fatty liver disease (NAFLD), coronary heart disease, metabolic syndrome, and T2DM." (PMID 36180826, 2022). "Fibroblast growth factor 21 (FGF21) is a unique member of the FGF family and has broad metabolic functions, including stimulating glucose uptake independent of insulin and improving hyperglycemia and dyslipidemia." (PMID 29854743, 2018).
Hyperglycemia (113 papers, 2011 to 2026). An increased concentration of glucose in the blood. "The correlation between FGF21 and DR incidence resembles hyperglycemia-associated adiponectin resistance." (PMID 39687000, 2024). "We demonstrated that Empagliflozin significantly improves stroke recovery, and this effect occurs in association with attenuated hyperglycemia, elevated serum FGF-21 levels and normalization in parenchymal pericyte density in the infarct core." (PMID 38424560, 2024). "In hyperglycemia-associated Phase I retinopathy mice, FGF21 (PF-05231023) decreased TFEB phosphorylation at serine 142, suggesting activation of the TFEB pathway by FGF21." (PMID 36943533, 2023). "We found that in mouse pups with induced insulin deficiency and postnatal hyperglycemia, liver production of FGF21 was decreased, suggesting the potential loss of metabolic regulation in immature liver." (PMID 36943533, 2023). "In hyperglycemia-associated Phase I retinopathy mice, we also found that FGF21 (PF-05231023) treatment decreased circulating triglyceride levels." (PMID 36943533, 2023). "Loss of FGF21 further attenuated physiological retinal vessel growth in hyperglycemia-associated vascular growth suppression (Phase I retinopathy) and also attenuated physiological retinal vessel growth under normoglycemic conditions." (PMID 36943533, 2023). "Here, we examined if FGF21 protects against hyperglycemia-associated delay of physiological retinal vessel growth in WT mice mediated through APN." (PMID 36943533, 2023). "Based on these findings, we propose that the mechanism of increased FGF21 levels in diabetic retinopathy is similar to those observed in hyperglycemia-associated resistance to adiponectin." (PMID 24895642, 2014). "Moreover, hyperglycemia causes dysregulation in the axis of fibroblast growth factor 21 (FGF21) and adiponectin." (PMID 39596980, 2024). "Hyperglycemia in neonatal mice which suppresses physiological retinal vascular growth is associated with decreased expression of systemic and retinal fibroblast growth factor 21 (FGF21)." (PMID 36943533, 2023). "Therefore, it is unsurprising that sustained hyperglycaemia is associated with increased FGF21 concentrations." (PMID 36415151, 2022). "In addition to the prevention of hyperglycaemia, which itself suppresses the beta cell loss, pancreatic islets are protected from glucolipotoxicity and cytokine-induced apoptosis by FGF21 treatment." (PMID 28770320, 2017). "Treatment of obese, hyperglycaemic, insulin-resistant and leptin-deficient B6-ob/ob mice with FGF21 could normalise hyperglycaemia despite markedly elevated endogenous FGF21 levels." (PMID 28770320, 2017). "It is important to mention that most other FGF family members (such as FGF21 and FGF23) have been widely reported for their association with hyperglycemia, whereas research on FGF4 remains relatively limited." (PMID 41347806, 2026). "FGF21, a stress-inducible circulating protein synthesized by the liver, followed the same pattern as hyperglycemia." (PMID 38750219, 2024). "The U-shaped response of IL-6, the rise of FGF-21 during hyperglycemia and the hyperglycemia-induced suppression of VEGF-A are in keeping with previous studies." (PMID 37400734, 2023). "Taken together with our previous report, FGF21 decreased hyperglycemia- and hyperoxia-induced retinal vascular suppression of Phase I retinopathy and reduced hypoxia-induced retinal neovascularization in Phase II." (PMID 36943533, 2023). "Our experimental investigations demonstrated that FGF21 reversed hyperglycemia-induced suppression of physiological retinal vascularization (Phase I retinopathy) by increasing circulating APN and modulating fatty acid oxidation." (PMID 36943533, 2023). "FGF-21 increased during both hypoglycemia and hyperglycemia while IL-6 and IL-10 increased during hypoglycemia." (PMID 37400734, 2023).
Hyperglycemia (continued). "Liver-specific PTP4A1 expression, followed by augmentation of FGF21 levels, reduced HF diet-induced hepatosteatosis and hyperglycemia in WT mice." (PMID 36793871, 2023). "In parallel, FGF21 activates thermogenic tissues and reduces adipose tissue inflammation, thereby protecting against adipose tissue dysfunction, hyperglycemia, and hypertriglyceridemia." (PMID 36648330, 2023). "Our newly calculated cut-off for total FGF-21 according to visceral adiposity identified subjects with fasting hyperglycemia." (PMID 37409233, 2023). "Fibroblast growth factor 21 (FGF21) alleviates high-fat high-cholesterol diet (HFCD)-induced hyperglycemia and hypertriglyceridemia." (PMID 36648330, 2023). "We found that FPG was significantly increased in those with increased FGF-21 levels, discriminating people with fasting hyperglycemia (105.82 mg/dL vs 148.65 mg/dL)." (PMID 37409233, 2023). "We found that liver and retinal mRNA expressions of FGF21 were lower in mouse neonates with hyperglycemia-induced suppression of physiological retinal vessel growth." (PMID 36943533, 2023). "Beneficial metabolic effects of exogenous FGF21 administration were also observed in obese or diabetic primates and in humans, although the improvements in hyperglycaemia were disappointingly modest in humans." (PMID 36064109, 2022). "FGF21 can tackle several important aspects of DM, by increasing insulin sensitivity, reducing hyperglycemia, improving the lipid metabolism profile of the blood, and inducing weight loss." (PMID 36699319, 2022). "STAM mice showed significant hyperglycemia and hypertriglyceridemia; higher phospholipid, FGF21, and AST levels; lower body weight; and higher liver weight, compared to normal C57BL/6J mice." (PMID 35203369, 2022). "Studies have shown that administration of FGF21 in a diabetic model reduces insulin resistance and reduces hyperglycemia by increasing the expression of transcription factors that stimulate the insulin gene." (PMID 36109786, 2022). "Gain and loss-of-function experiments identified a regulatory pathway in adipocytes involving miR-21a-3p, FGFR1, FGF21, and PPARγ that regulated adipocyte browning and participated in hyperglycemia-induced atrial fibrosis." (PMID 34484568, 2021). "FGF21 is more abundant in the liver than in adipose tissues, explaining why some patients with p.Tyr95Cys have hyperglycemia but mild hypertriglyceridemia and lipoatrophy." (PMID 34764936, 2021). "Here we show that increases in circulating FGF21 levels and expression of hepatic FGF21 preceded weight gain, hyperinsulinemia, and hyperglycemia in C57BLJ6 mice fed a high-fat diet." (PMID 32978487, 2020). "Up‐regulation of FGF21 seems a compensatory mechanism to protect against hyperglycaemia‐induced cardiomyopathy and acetaminophen‐induced acute liver injury." (PMID 32227589, 2020). "Of note, FGF21 has been shown to reduce levels of inflammatory mediators including IL-1β, IL-6 and TNFα in the serum of obese/diabetic db/db mice and ameliorates hyperglycemia." (PMID 31312114, 2019). "Functionally, overexpression of FGF21 attenuated hyperglycaemia and insulin storage, improved glucose tolerance and preserved islet β‐cells from apoptosis." (PMID 30461198, 2019). "The beneficial effect of FGF21 on islet β‐cells was further confirmed by our findings that AAV‐FGF21 treatment attenuated hyperglycaemia and ameliorated glucose intolerance in db/db mice." (PMID 30461198, 2019). "According to available studies, human serum FGF21 levels are increased by oral boluses of fructose and glucose and by 24-h hyperglycemia maintained via intravenous glucose infusion." (PMID 30959789, 2019). "Only LP/HF mice are protected against hyperglycaemia, whereas LP/HC mice showed an increased blood glucose, but both LP/HF and LP/HC mice exhibited increased circulating levels of FGF21." (PMID 29550873, 2018).
Hyperglycemia (continued). "In summary, prevention of hyperglycaemia through protein restriction is compromised by high dietary carbohydrates despite increased FGF21 levels." (PMID 29550873, 2018). "FGF21 treatment prevented islet destruction and the onset of hyperglycaemia, and improved glucose clearance." (PMID 28770320, 2017). "In contrast, the absence of this correlation in children of mothers with GDM may indicate that fetal hyperglycemia limits the usefulness of FGF-21 as an indicator of postnatal growth in this group." (PMID 40648894, 2025). "Moreover, studies with the liver‐specific insulin receptor KO (LIRKO) model revealed FGF21 treatment to normalise hyperglycaemia in mice by increasing energy metabolism in brown fat." (PMID 39962359, 2025). "Whether FGF21 has the potential to be used in the treatment of hyperglycemia also requires further exploration." (PMID 39819596, 2025). "Additionally, FGF21 is further increased by hyperglycemia, showing a positive reaction to PPAR gamma." (PMID 39596980, 2024). "However, the protective effects of FGF21 appear to be most significant in the early stages of hyperglycemia, as FGF21 appears to be elevated in chronic hyperglycemia as a compensatory or resistance effect." (PMID 39687000, 2024). "Furthermore, hepatic FGF21 overexpression ameliorated hyperglycemia and hypertriglyceridemia by activating thermogenic tissues and reducing adipose tissue inflammation." (PMID 37576954, 2023). "Moreover, individuals with FGF-21 level above this cut-off also presented with fasting hyperglycemia." (PMID 37409233, 2023). "Loss of APN did not affect hyperglycemia in FGF21 vs. vehicle-treated Phase I retinopathy mice (blood glucose averaged 150 to 160 mg/dl)." (PMID 36943533, 2023). "Interestingly, we also found that hyperglycemia increased in neonatal mice co-treated with FGF21 (PF-05231023) and etomoxir (292.4 ± 30.51 mg/dl) vs. FGF21 (PF-05231023) and vehicle (DMSO, 186.6 ± 15.29 mg/dl, P = 0.0159)." (PMID 36943533, 2023). "Next, we tested whether FGF21 overexpression in Ptp4a1-/- mice could ameliorate an HF diet-induced hyperglycemia and NAFLD." (PMID 36793871, 2023). "FGF21 prevented hepatic lipotoxicity, accompanied by activation of thermogenic tissues and attenuation of adipose tissue inflammation, improvement of hyperglycemia and hypertriglyceridemia, and upregulation of hepatic programs involved in fatty acid oxidation and cholesterol removal." (PMID 36648330, 2023). "Interestingly, both TNF-α and IL-6 have been shown to increase similarly during experimental hyperglycemia along with rises in IL-18 and FGF-21 and suppression of VEGF." (PMID 37400734, 2023). "On the other hand, FGF-21 can alleviate inflammation while improving hyperglycemia." (PMID 36594101, 2023). "One of the major effects of FGF21 is lowering hyperglycemia." (PMID 36699319, 2022). "Furthermore, both groups showed the correlation between FGF21 level and hyperglycemia, hypertriglyceridemia and lowered HDL which were metabolic components that were significantly correlated to FGF21 level." (PMID 36474191, 2022). "FGF21 may increase earlier than we are generally aware, and this increase may precede the hyperglycemia of GDM." (PMID 33995273, 2021). "Furthermore, FGF21 overexpression significantly inhibited the hyperglycemia-induced clonal formation in the LNCaP cells." (PMID 33753729, 2021). "The whey protein isolate-induced normalization of hepatic FGF21 production may contribute to the improvement of hyperinsulinemia and hyperglycemia in mice fed a high-fat diet." (PMID 32978487, 2020). "However, LT completely retarded the development of hyperglycaemia, reduced hypertriglyceridemia, and increased serum FGF21 levels, in this model." (PMID 32518324, 2020).